DOT1L (DOT1 like histone lysine methyltransferase)
Diseases named in the same sentence as DOT1L in open-access papers (continued):
Sharing a sentence is not in itself a finding about the gene and the disease.
infection (continued). "These mice were subsequently challenged with a range of immunogens as well as several models of a bone fide infection, such as influenza and the Lymphocytic Choriomeningitis virus (LCMV), to assess the effects of deleting Dot1l on antigen-dependent B cell differentiation in different contexts." (PMID 38962004, 2024). "As Dot1L regulates the innate immune response, we analyzed the impact of Dot1L inhibition during infection with a PR8 strain that does not express the NS1 protein (delNS1virus, PR8ΔNS1)." (PMID 32188146, 2020). "In contrast to PR8 infection, viral replication, the activation of IFN-β-driven expression, RIG-I-MAVS association, and NF-kB nuclearization are not affected by Dot1L inhibition in delNS1 infection." (PMID 32188146, 2020). "The recruitment of RIG-I to mitochondrial fractions was not modified by Dot1L inhibition in delNS1 infection." (PMID 32188146, 2020). "Dot1L inhibition did not significantly reduce NF-κB relocalization in delNS1 infection." (PMID 32188146, 2020). "Since EPZ004777 specifically inhibits DOT1L and not Rv2067c, macrophages were treated with EPZ004777 prior to infection." (PMID 38129415, 2023). "Infection of MDCK Npro cells did not increase IFNβ, ISG56 or Mx1 RNAs, independently of the presence of Dot1L inhibitor (bottom), which coincided with the inability of these cells to produce IFN and ISG." (PMID 29352168, 2018).
hematological malignancies (7 papers, 2016 to 2024). "DOT1L is also an HMT, and clinical trials using the DOT1L inhibitor EPZ‐5676 for hematological malignancies are also in progress." (PMID 37220590, 2023). "Currently, clinical trial has been initiated with a potent DOT1L inhibitor EPZ-5676 for the treatment of hematological malignancies." (PMID 27531902, 2016). "In fact, compounds blocking DOT1L activity or impairing binding between KMT2A-AF4 aberrant protein and its cofactor Menin are already undergoing clinical trials for the treatment of hematological diseases, with the promise of a novel treatment for BCP-ALL in the near future." (PMID 33803872, 2021).
kidney diseases (2 papers, 2019 to 2022). "Currently, DOT1L expression in human kidney disease remains unclear and requires further investigations." (PMID 31866860, 2019). "Key lysine and arginine methyltransferases under investigation for renal disease treatment include EZH2, G9a, DOT1L, PRMT1 and PRMT5." (PMID 35559246, 2022). "Finally, although clinical trials of some EZH2 and DOT1L inhibitors for treatment of tumors have been reported, there are still no clinical trials for HMT inhibitors in renal diseases." (PMID 31866860, 2019).
cardiovascular diseases (1 paper, 2022). "Previous researches have demonstrated that a variety of epigenetic mechanisms was widely involved in cardiovascular diseases (CVDs), as an important branch of epigenetic pathway, the role of Dot1L-mediated H3K79 methylation in CVDs is gradually revealed." (PMID 35986422, 2022).
heart diseases (1 paper, 2022). "There is a reasonable prospect that Dot1L would have enormous therapeutic potential in heart diseases coupled with in-depth knowledge of underlying mechanism of CVDs." (PMID 35986422, 2022).
DOT1L also shares sentences with these, for which no sentence is quoted: clear cell renal carcinoma (3 papers); chronic kidney disease (2); gastric tumors (2); glioma (2); rectal adenocarcinoma (2); acute monocytic leukemia (1); adenocarcinoma (1); Autoimmunity (1); benign ovarian tumors (1); blood cancer (1); breast (1); Burkitt lymphoma (1); colorectal adenoma (1); cutaneous T cell lymphoma (1); depression (1); diffuse large B-cell lymphoma (1); epithelioid sarcoma (1); esophageal squamous cell carcinoma (1); follicular lymphoma (1); Hepatic fibrosis (1); Hutchinson-Gilford progeria syndrome (1); Hypertension (1); intraepithelial neoplasia (1); invasive breast carcinoma (1); invasive ductal carcinomas (1); lymphedema (1); metastatic carcinoma (1); myeloid malignancies (1); neurological diseases (1); nut midline carcinoma (1).
A further 8 diseases each share a sentence with DOT1L in 1 paper.